APP (amyloid beta precursor protein)
Diseases named in the same sentence as APP in open-access papers (continued):
Sharing a sentence is not in itself a finding about the gene and the disease.
Alzheimer disease (continued). "Given that Aβ is produced by cleavage of APP by β- and γ-secretase, γ-secretase inhibition is a promising disease modifying treatment for Alzheimer's disease." (PMID 23573456, 2013). "β-amyloid precursor protein (APP) is a key factor in Alzheimer's disease (AD) but its physiological function is largely undetermined." (PMID 24224055, 2013). "APP is also a target for miRNA regulation, miR-106a and miR-106b directly bind to APP mRNA and are down regulated in the anterior temporal cortex of Alzheimer's disease patients." (PMID 24133413, 2013). "Misfolded proteins are able to induce tissue damage via protein fibrillation like the Amyloid Precursor Protein (APP) in Alzheimer Disease." (PMID 23940647, 2013). "In individuals with Alzheimer’s disease Zn(II) would bind to the ferroxidase site in the E2 domain of APP and inhibits its ferroxidase activity, resulting in accumulation of intracellular Fe(II) and subsequent oxidative damage of the cells." (PMID 23977245, 2013). "AIDA1 derives its name from the ability to bind the carboxy terminal cytoplasmic region of amyloid precursor protein (APP), widely implicated in the development of Alzheimer’s disease." (PMID 23799029, 2013). "The lncRNAs within the mRNA sequences in Alzheimer's disease genes, namely, APP or AD1, APOE or AD2, PSEN1 or AD3, and PSEN2 or AD4, have been analyzed in terms of fractal dimension computation and correlation analysis." (PMID 23662159, 2013). "Thus genes such as RUNX1 (which may contribute to childhood leukaemia in people with DS), APP (a key Alzheimer disease gene) and SYNJ1, RCAN1 and ITSN1, which have been linked to endosomal/synaptic abnormalities are unlikely to contribute to the phenotype of this mouse model of DS." (PMID 23596509, 2013). "Generation of the amyloid β peptide (Aβ) from the amyloid precursor protein (APP) and the subsequent aggregation of Aβ as soluble synaptotoxic oligomers, is central to the pathogenesis of Alzheimer's Disease (AD)." (PMID 24205136, 2013). "In Alzheimer’s disease and type II diabetes it was shown that the amyloid precursor protein (APP) peptide directly binds to the gangliosides in the brain lipid rafts and most probably to the lipid rafts in the pancreas." (PMID 23555611, 2013). "A key event in the pathogenesis of Alzheimer’s disease (AD) is the accumulation of amyloid-β (Aβ) species in the brain, derived from the sequential cleavage of the amyloid precursor protein (APP) by β- and γ-secretases." (PMID 23520537, 2013). "Amyloid precursor protein (APP), a transmembrane glycoprotein, is well known for its involvement in the pathogenesis of Alzheimer disease of the aging brain, but its normal function is unclear." (PMID 23691241, 2013). "Soluble oligomeric amyloid β peptide (Aβ) generated from processing of the amyloid precursor protein (APP) plays a central role in the pathogenesis of Alzheimer's Disease (AD) and through actions at glutamatergic synapses affects excitability and plasticity." (PMID 24205136, 2013). "Amyloid beta (Aβ) peptides produced by APP cleavage are central to the pathology of Alzheimer’s disease." (PMID 24244667, 2013). "Autosomal-dominant Alzheimer disease (ADAD) is a genetic disorder that accountsfor less than 1 % of all AD cases.It is genetically heterogeneous and has been associated with mutations in theamyloid precursor protein (APP) gene or in thetwo presenilin genes (presenilin-1 and -2 or PSEN1 and PSEN2)." (PMID 23224319, 2013). "For example, the final coding exon of the amyloid beta (A4) precursor protein gene (APP), implicated in Alzheimer’s disease, is repositioned by a rearrangement and relocated to the other Tc1 Hsa21 chromosome arm in relation to the rest of the gene." (PMID 23596509, 2013). "Alzheimer’s disease (AD) is characterized by extracellular accumulation of amyloid-β peptide (Aβ), generated by proteolytic processing of the amyloid precursor protein (APP) by β- and γ-secretase." (PMID 23485990, 2013).
Alzheimer disease (continued). "In a network-based study similar to this, APP was identified as a negative regulator of insulin abundance in plasma of mice and a potential link between Alzheimer's disease and type 2 diabetes was suggested." (PMID 24376773, 2013). "Aβ is an approximately 40–42 amino acid peptide that is derived from APP by proteolytic processing and which is deposited in the brains of Alzheimer's disease patients within amyloid plaques." (PMID 23825109, 2013). "SORLA and SORCS1 act as neuronal receptors for the amyloid precursor protein (APP) controlling proteolytic breakdown of this precursor into neurotoxic amyloid-β peptides, a pathological mechanism in Alzheimer’s disease." (PMID 24069373, 2013). "Amyloid beta (Aβ) is generated from amyloid precursor protein (APP) and accumulates in the senile plaques of Alzheimer's disease patients." (PMID 24312169, 2013). "The amyloid precursor protein (APP) is a key axonal transport cargo in Alzheimer's disease since perturbation of its transport increases APP processing and production of amyloid-β peptide (Aβ) that is deposited in the brains of Alzheimer's disease patients." (PMID 23825109, 2013). "Similar astrocyte calcium waves have been observed to occur spontaneously under pathophysiological conditions in vivo in an APP/PS1 mouse model of Alzheimer's disease." (PMID 23847529, 2013). "We were stimulated to do this by the clear evidence that the distribution of pathogenic mutations in amyloid precursor protein (APP) and presenilin in Alzheimer's disease gives insight into their mode of pathogenicity." (PMID 23669636, 2013). "SORLA is best recognized for its role as a sorting receptor for the amyloid precursor protein (APP), the main etiologic agent in Alzheimer disease (AD)." (PMID 23977241, 2013). "In this report, we sought proof that the use of APP translation blockers can reduce amyloid expression pertinent to providing therapy for individuals afflicted with Alzheimer's disease (AD) and Down syndrome (DS)." (PMID 23935819, 2013). "Previous works showed that this protein is up-regulated in Alzheimer’s disease (AD), and plays an active role in the development of brain amyloidosis in the APP transgenic mice." (PMID 23951061, 2013). "Alzheimer’s disease (AD) is characterized by the buildup of amyloid-β peptides (Aβ) aggregates derived from proteolytic processing of the β-amyloid precursor protein (APP)." (PMID 24376644, 2013). "Virtually all Down syndrome (DS) adults develop progressive neurodegeneration as seen in Alzheimer's disease (AD), and overexpression of the amyloid precursor protein (APP), a gene located on chromosome 21, is thought to contribute to AD in DS." (PMID 24086147, 2013). "The discovery of monogenic forms of Alzheimer's Disease (AD) associated with mutations within PSEN1, PSEN2, and APP genes is giving a big contribution in the understanding of the underpinning mechanisms of this complex disorder." (PMID 24377094, 2013). "APP is a central component of Alzheimer’s disease (AD), where its cleavage generates β-amyloid peptides." (PMID 23874584, 2013). "Recent research in Alzheimer’s disease (AD) field has been focused on the potential role of the amyloid-β protein that is derived from the transmembrane amyloid precursor protein (APP) in directly mediating cognitive impairment in AD." (PMID 23663320, 2013). "Despite the extensive mechanistic and pathological characterization of the amyloid precursor protein (APP)/presenilin-1 (PS-1) knock-in mouse model of Alzheimer's disease (AD), very little is known about the AD-relevant behavioral deficits in this model." (PMID 23705774, 2013). "Amyloid precursor protein (APP) proteolysis is required for production of amyloid-β (Aβ) peptides that comprise β-amyloid plaques in brains of Alzheimer’s disease (AD) patients." (PMID 23409038, 2013). "(E)-5-(4-iodostyryl)-1H-indole clearly stained Aβ plaques in the brain sections of Alzheimer’s disease (AD) model mice (APP/PS1)." (PMID 22491675, 2012).
Alzheimer disease (continued). "The interaction of tau with APP and its proteolytic fragments in the progression of Alzheimer’s disease has been shown in numerous studies (reviewed)." (PMID 23028730, 2012). "Numerous prior studies support the interaction of APP and tau in progression of Alzheimer’s disease." (PMID 23028730, 2012). "Overall, then, identifying functional interactions between APP and PrP has substantial and diverse implications for Alzheimer Disease and prion disease research." (PMID 23236467, 2012). "The β site APP cleaving enzyme 1 (BACE1) is the rate-limiting β-secretase enzyme in the amyloidogenic processing of APP and Aβ formation, and therefore it has a prominent role in Alzheimer’s disease (AD) pathology." (PMID 22952813, 2012). "Taken together, data obtained both in single and in multi-compartment models strongly suggested that depletion of APP dimer processing represents a major molecular mechanism in the pathology of Alzheimer’s disease." (PMID 22727043, 2012). "Unfortunately, reports confirming the role of APP and Aβ peptides in the normal retina and in the retina of patients with Alzheimer's disease are limited." (PMID 22279552, 2012). "People who inherit mutated APP, PS1, or PS2 genes are very likely to develop Alzheimer's disease at some point in their lives." (PMID 22482075, 2012). "Tissue sections from Alzheimer’s disease patient brains show distinctive intracellular neurofibrillary tangles and extracellular amyloid plaques composed of beta-amyloid derived from amyloid precursor protein (APP)." (PMID 23267366, 2012). "The main pathological hallmarks of Alzheimer’s disease are amyloid-beta plaques and neurofibrillary tangles, which are primarily composed of amyloid precursor protein (APP) and tau, respectively." (PMID 23028730, 2012). "The manner by which Tyro3 receptors influence APP processing and Aβ accumulation in the progression of Alzheimer's disease requires further study." (PMID 22701746, 2012). "β-site amyloid precursor protein-cleaving enzyme (BACE) is a membrane-bound aspartic protease that cleaves the amyloid precursor protein (APP) in the pathogenesis of Alzheimer's disease." (PMID 22449099, 2012). "This resembles the β-amyloid precursor protein (APP) in Alzheimer disease (AD), which can be physiologically processed by α-, β-, and γ-secretases." (PMID 23202518, 2012). "β-site APP cleaving enzyme 1 (BACE1) cleaves β-amyloid precursor protein (APP) to initiate the production of β-amyloid (Aβ), the prime culprit in Alzheimer’s disease (AD)." (PMID 22709416, 2012). "APP is well known for its role in pathology, as its cleavage product Aβ peptide is the key component of amyloid plaques in Alzheimer's disease." (PMID 22279552, 2012). "Cleavage of APP by γ-secretase leads to the formation of Aβ peptides, which is the main pathology of Alzheimer’s disease." (PMID 22727043, 2012). "Transgenic models based on APP overexpression have been extraordinarily successful in recapitulating the late-onset pathology of Alzheimer’s disease within the two-year lifespan of the laboratory mouse." (PMID 22709352, 2012). "miR-101 reduced APP expression after prolonged IL-1β treatment, suggesting a role for miR-101 in the control of APP expression in response to IL-1β in Alzheimer's disease." (PMID 22312330, 2012). "One of these is amyloid protein precursor (APP) and in a murine model of early-onset Alzheimer's disease the authors found a decrease in miR-16-5p levels while APP was increased." (PMID 23144617, 2012). "In research to develop improved treatments for Alzheimer’s disease, there has been considerable investigation of the cleavage of APP and APLP2, and inhibitors of β-secretases have been developed that block the cleavage of these proteins." (PMID 22797723, 2012). "Human β-amyloid precursor protein (APP) is generally thought to play a key role in Alzheimer's disease as the source of plaque-forming β-amyloid peptides (Aβ)." (PMID 22916096, 2012).
Alzheimer disease (continued). "Amyloid precursor protein (APP) is a transmembrane glycoprotein frequently studied for its role in Alzheimer's disease." (PMID 22279552, 2012). "Amyloid-β-protein (Aβ), the key component of senile plaques in Alzheimer's disease (AD) brain, is produced from amyloid precursor protein (APP) by cleavage of β-secretase and then γ-secretase." (PMID 23211096, 2012). "In Alzheimer's disease, the Aβ peptide and the amyloid precursor protein (APP)-derived fragment (APP-CTF) are cleared upon autophagy induction." (PMID 21930185, 2012). "A similar γ-secretase was found in the transmembrane domain of APP, which is important in the last step of amyloid-β protein production, which is thought to contribute to the pathogenesis of Alzheimer’s disease." (PMID 23251561, 2012). "In summary, we have provided a cross-validated study for feasible small-animal PET imaging of Aβ plaque deposition with [11C]PiB in an APP/PS1 mouse model of Alzheimer's disease." (PMID 22427802, 2012). "Non-coding DNA in and around the human Amyloid Precursor Protein (APP) gene that is central to Alzheimer’s disease (AD) shares little sequence similarity with that of appb in zebrafish." (PMID 22947103, 2012). "The amyloid precursor protein (APP) is a type-1 membrane protein expressed in neurons, which is closely linked to the etiology and pathology of Alzheimer’s disease (AD)." (PMID 22727043, 2012). "Amyloid precursor protein (APP), a key molecule in Alzheimer’s disease (AD), is metabolized in two alternative cleavages, generating either the amyloidogenic peptides involved in AD pathology or the soluble form of APP (sAPPα)." (PMID 22824057, 2012). "Amyloid precursor protein cleaving enzyme 1 (BACE1), an aspartyl protease, initiates processing of the amyloid precursor protein (APP) into β-amyloid (Aβ); the peptide likely contributes to development of Alzheimer’s disease (AD)." (PMID 23133641, 2012). "The formation of Aβ peptides from the amyloid precursor protein (APP) is a crucial event in Alzheimer’s disease (AD)." (PMID 22970285, 2012). "In this study we examined the effects of 56Fe particle irradiation in an APP/PS1 mouse model of Alzheimer’s disease (AD)." (PMID 23300905, 2012). "Most studies for APP have focused on its link to the pathogenesis of Alzheimer’s disease (AD), with the cleavage products of APP known to be a significant component of amyloid plaques observed in both the aging and AD brain." (PMID 22912823, 2012). "The aspartyl protease, γ-secretase, is a multisubunit protease which mediates the coordinated intramembrane proteolysis of both Notch and amyloid-precursor protein (APP), which are both implicated in the etiology of Alzheimer's disease (AD)." (PMID 22754566, 2012). "Amyloid precursor protein (APP) plays a pivotal role in Alzheimer’s disease (AD) pathogenesis, but its normal physiological functions are less clear." (PMID 22545081, 2012). "Proteolytic breakdown of the amyloid precursor protein (APP) by secretases is a complex cellular process that results in formation of neurotoxic Aβ peptides, causative of neurodegeneration in Alzheimer’s disease (AD)." (PMID 22727043, 2012). "This is true for HTT, the β-amyloid precursor protein (APP) and presenilins, responsible for early onset Alzheimer's disease (AD)." (PMID 22489754, 2012). "Amyloid precursor protein (APP) has been a focus of intense investigation because of its central role in Alzheimer’s disease (AD) pathogenesis." (PMID 22545081, 2012). "The Aβ peptide that accumulates in Alzheimer’s disease (AD) is derived from amyloid precursor protein (APP) following proteolysis by β- and γ-secretases." (PMID 22734645, 2012). "The amyloid precursor protein (APP) plays a central role in the pathophysiology of Alzheimer's disease in large part due to the sequential proteolytic cleavages that result in the generation of β-amyloid peptides (Aβ)." (PMID 21527012, 2011).
Alzheimer disease (continued). "In 22 DNA samples from individuals diagnosed with clinical Alzheimer disease, we identified one patient carrying a duplication on chromosome 21 which included the APP locus." (PMID 22044463, 2011). "Such dynamic interactions between APP and HSV1 suggest a mechanistic basis for the observed clinical relationship between HSV1 seropositivity and risk of Alzheimer's disease." (PMID 21483850, 2011). "To test binding specificity of the delivered protein, we mixed an antibody against amyloid beta peptide (4G8) with K16ApoE and injected the mixture intravenously into APP/PS1 mice (a model for Alzheimer's disease)." (PMID 22216132, 2011). "Processing of Aβ-precursor protein (APP) plays an important role in Alzheimer's Disease (AD) pathogenesis." (PMID 21445342, 2011). "The amyloid β-peptide, which forms amyloid plaques in the brain of people with Alzheimer’s disease, is the product of sequential cleavage of a single-span membrane amyloid precursor protein (APP)." (PMID 22649674, 2011). "One of the hallmarks of Alzheimer's disease, and several other degenerative disorders such as Inclusion Body Myositis, is the abnormal accumulation of amyloid precursor protein (APP) and its proteolytic amyloid peptides." (PMID 21518451, 2011). "In this study, we have focused on the novel role of X11s in the intracellular transport of APP, because Aβ, which is a major factor in the pathogenesis of Alzheimer's disease, is generated from the proteolytic cleavages of APP during protein secretory pathway." (PMID 21818298, 2011). "Despite its key role in Alzheimer's disease (AD) pathogenesis, the physiological functions of the β-amyloid precursor protein (APP) and its close homologue, the β-amyloid precursor-like protein 2 (APLP2), are still poorly understood." (PMID 21435241, 2011). "The cleavage of APP is intensively studied, as APP is the precursor for the amyloid β peptide (Aβ), which has a key role in Alzheimer's disease (AD) pathogenesis." (PMID 21695060, 2011). "FE65 binds the intracellular tail of APP, domains of which appear to play key roles in the pathogenesis of Alzheimer Disease." (PMID 20436672, 2010). "Overexpression of Pin1, a member of the parvulin family of immunophilins, reduces Aβ and knockout of Pin1 increases Aβ production in Alzheimer's disease brains, through the isomerization of the cytoplasmic domain of APP at a phosphorylated Thr668/Pro motif." (PMID 20084280, 2010). "γ-Secretase is an intramembrane aspartyl protease which plays a pivotal role in Alzheimer's disease since it mediates the release of the amyloid β-peptide (Aβ) from the amyloid precursor protein (APP)." (PMID 20333303, 2010). "Metal dys-homeostasis is instrumental in the pathology of Alzheimer's disease and copper interactions with APP and Aβ, both of which contain copper-binding sites, have been widely documented and implicated in the disease –[14; reviewed in 15]." (PMID 20084280, 2010). "Regulated intramembranous proteolysis of the amyloid-β precursor protein by the γ-secretase yields amyloid-β, which is the major component of the amyloid plaques found in Alzheimer's disease (AD), and the APP intracellular domain (AID)." (PMID 20661273, 2010). "A central feature of Alzheimer's disease is the cleavage of the amyloid precursor protein (APP) to form beta-amyloid peptide (Aβ) by the β-secretase and γ-secretase enzymes." (PMID 20409323, 2010). "The metabolism of amyloid precursor protein (APP) and β-amyloid (Aβ) is widely studied in Alzheimer's disease, where Aβ deposition and plaque development are essential components of the pathogenesis." (PMID 20569437, 2010). "The APP[V717I] London (APP-Ld) mouse model recapitulates important pathological and clinical hallmarks of Alzheimer's disease (AD) and is therefore a valuable paradigm for evaluating therapeutic candidates." (PMID 20862386, 2010).